CD4 (CD4 molecule)
Diseases named in the same sentence as CD4 in open-access papers (continued):
Sharing a sentence is not in itself a finding about the gene and the disease.
COVID-19 (continued). "We found higher frequencies of neutrophils, intermediate CD14+CD16+monocytes, activated HLA-DR+CD38+, EM-like CD4+ and CD8+ T-cells in COVID-19 respiratory compared to blood samples, and similar immune responses with dexamethasone (with/without remdesivir) treatment." (PMID 34462740, 2021). "The associations between (i) the differences in disease severity and prevalence between men and women and (ii) the differences in CD4+ and CD8+ T cell counts between male and female COVID-19 patients remain unclear." (PMID 33350432, 2021). "Similarly to SARS-CoV-1, lymphopenia with drastically reduced CD4+ and CD8+ T cells is the most consistent finding in moderate-to-severe COVID-19 patients, and it correlates with disease severity and mortality." (PMID 33996683, 2021). "Interestingly, plasmacytoid dendritic cell cluster DC_c4 − LILRA4, T_CD4_c04 − ANXA2, T_c14_gdT-TRDV2 (γδ T cells), T_CD8_c09-SLC4A10, and T_CD8_c08-IL2RB clusters were decreased in the progression stage of severe COVID-19 patients." (PMID 33863870, 2021). "It is possible that the persons with high levels of pre-existing memory CD4+ T cells could recognize SARS-CoV-2 and could mount the faster response upon exposure to SARS-CoV-2 and thereby limiting COVID-19 severity." (PMID 33937545, 2021). "In the CD4+ T cells of COVID-19 patients at the two-week convalescent stage, 37 unique pairs of VJ rearrangement of TRA were found, such as TRAV8-4/TRAJ54 and TRAV17/TRAJ54, and 23 specific pairs of TRB VDJ patterns were also found in CD4+ T cells." (PMID 35011632, 2021). "Both CD4+T and CD8+T cells were activated and inflammatory in early phase (stage A) and accumulated mature and memory T cells during convalescent process (stage B), which were critical for recovery from COVID-19." (PMID 35095832, 2021). "We also showed that normal CD4+ T cells constructed with B65-targeted TCRs exhibit functional reactivity against SARS-CoV-2 S. Our study provided valuable information for developing potential vaccines and new treatment strategies against COVID-19." (PMID 34805136, 2021). "In the subgroup of COVID-19 patients with obesity, compared to the nonsevere group, the levels of CD4 were significantly decreased in the severe group." (PMID 33746594, 2021). "In parallel, significantly lower levels of naïve Th (CD3+CD4+CD45RA+) and naïve Ts (CD3+CD8+CD45RA+) cells were observed from admission to day 7 in the ICU COVID-19 patients (p = 0.043 and p < 0.001, respectively, for naïve Th, and p < 0.001 and p = 0.006, respectively, for naïve Ts cells)." (PMID 34071149, 2021). "Specifically, total CD3+ T-lymphocyte, CD3 + CD4+ subset absolute counts and the TLSI were independent predictors of in-hospital mortality, together with older age, male gender, increased LDH and creatinine plasmatic levels, in COVID-19 hospitalized patients." (PMID 34140530, 2021). "In summary, the main findings of this study were that it was the CD8+T cell level, not the CD4+T cell level, reflected the severity of the disease, and that decreased CD4+T cell level were important in predicting the prognosis of COVID-19 patients." (PMID 33435865, 2021). "In patients with severe COVID-19, high levels of circulating IL-6, IL-1β, INFγ, and TNF-α have been reported, together with an unbalanced white cell formula, consisting of high neutrophils and decreased CD4+ and CD8+ T cells." (PMID 35140702, 2021). "Data from recovered COVID-19 patients show that memory CD8+ T cells were found in approximately 70% of the recovered individuals, with 100% of the recovered individuals having memory CD4+ T cells." (PMID 34681059, 2021). "A second diversion of the adaptive immune response by SARS-CoV-2 is T-cell atrophy or absence of the virus-specific CD4+ T cells in severe COVID-19 patients." (PMID 34737743, 2021).
COVID-19 (continued). "However, in COVID-19 patients with concomitant aTB, SARS-CoV-2–specific CD4+ T cells displayed lower polyfunctional capacity, characterized by significant reduction of the cells with 3 functions, compared with HIV–/aTB– patients." (PMID 33945513, 2021). "It is worth keeping track of whether the number or frequency of CD4+ and/or CD8+ T cells in peripheral blood and pulmonary inflammatory tissue decrease in obese patients with severe COVID-19." (PMID 34373739, 2021). "The power of this unique feature was demonstrated in the context of COVID-19 where the pools of peptides identified from three SARS-CoV-2 proteins were demonstrated to induce both CD4 and CD8 responses in the vast majority of tested COVID-19 positive individuals." (PMID 34484239, 2021). "The percentage of Th1 (CD4+IFN-γ+) cells was not altered in COVID-19 patients, although the total number of Th1 cells was lower in severe COVID-19 patients compared to healthy donors due to lymphocytopenia (data not shown)." (PMID 33692788, 2021). "Surprisingly, higher magnitude of Non-spike reactive CD4+ T cells were also present in the unexposed donors as in recovered COVID-19 patients (Unexposed vs COVID-19, P=0.001)." (PMID 33777028, 2021). "In addition, patients with severe COVID-19 also showed a reduction in total CD4+ T cells, CD8+ T cells, B cells, and NK cells compared to mild and/or moderate COVID-19 patients." (PMID 34359987, 2021). "Specifically, CD8+ T cell, but not CD4+ T cell, reduction by SARS-CoV-2 is associated with a worse prognosis in COVID-19 patients." (PMID 34945761, 2021). "The signaling pathways regulating metabolic processes, including the TGF-beta signaling pathway, HIF-1 signaling pathway, FoxO signaling pathway, cAMP signaling pathway, and PI3K-Akt signaling pathway, were mostly downregulated in the subsets of CD4+ and CD8+ T cells in COVID-19 patients." (PMID 33936072, 2021). "Our early COVID-19 case study revealed that both ICOS+PD-1+CD4+ TFHs and activated CD38+HLA-DR+ CD4+/CD8+ T cells appeared transiently in patient's blood at 3 days prior to recovery, suggesting involvement of T cells in the resolution of COVID-19." (PMID 35004764, 2021). "In CD8+ T cells — but not in CD4+ T cells — the PD-1 miRNet was also found to be altered, as shown by the higher expression of miR–15a-5p in patients who recovered from COVID-19 and in patients with COVID-19 as compared with healthy controls." (PMID 34784300, 2021). "It is noteworthy that the T cell and CD4+ T cell but not CD8+ T cell were significantly decreased in severe COVID-19 patents, which suggested that CD4+ T cell but not CD8+ T cell play more important role in immunity response to SARS-CoV-2 infection." (PMID 34210280, 2021). "In COVID-19 patients, AREG is significantly upregulated in PBMCs65, monocytes, CD4 T Cells, NK cells, neutrophils, and DCs61, suggesting that upregulation of AREG may be an attempt to ameliorate the severe injury induced by SARS-CoV-2 infection." (PMID 34262047, 2021). "Moreover, post COVID-19 Ab− had significantly higher tp HCoV-OC43 S N-terminal reactive T cells (p = 0.05) and post COVID-19 Ab+ less tp HCoV-OC43 S C-terminal reactive CD4+ T cells." (PMID 34322120, 2021). "CD4 and CD8 T cells had increased expression of PD1 in both groups of COVID-19 patients." (PMID 33692788, 2021). "Given that lymphopaenia is known to be a feature of viral infection, rather than unique to severe COVID-19 we searched for observational studies that had measured CD4 and CD8 counts in other respiratory viral infections." (PMID 35965490, 2021). "After stimulation with spike S-I and S-II peptide pools, COVID-19 convalescents showed high frequencies of S-I– and S-II–activated CD4+ T cells that largely lacked CD3 expression characteristic of cognate T cell activation." (PMID 34465633, 2021).
COVID-19 (continued). "In mild COVID-19, CD8+ resident-memory (TRM) and CD4+ T-helper-17 (TH17) cells undergo active (presumably antigen-driven) expansion towards the end of the trajectory, and are characterized by good effector functions, while in critical COVID-19 they remain more naïve." (PMID 33473155, 2021). "Again, the overall magnitude of the SARS-CoV-2-specific CD4+ T cell response was not impacted by the duration of COVID-19 symptoms." (PMID 34063463, 2021). "In this study, we collected blood from virus-free COVID-19 convalescent individuals to explore the immune response of host cells, and analyzed their SARS-CoV-2-specific antibody and the response of CD4+, CD8+, and natural killer (NK) cells to SARS-CoV-2 antigen peptide pools." (PMID 34234102, 2021). "Antigen-specific CD4+ T cells expressing memory markers as well as IL-2, IFN-γ, TNF-α, and CD154 were markedly increased in COVID-19–recovered individuals compared with healthy donors, but the relative frequency of these cells decreased at the 6.1-mo time point (clusters 2, 3, 4, and 6)." (PMID 33533915, 2021). "Severe COVID-19 patients were highly dynamic in MAPK cascade, NF-κB signaling, T cell receptor signaling and positive regulation of cytokine production for both NK cells and CD4+ T cells." (PMID 34845446, 2021). "COVID-19 children without or with mild/moderate clinical manifestations showed similar frequencies of activated CD4 and CD8 cells compared to age-matched control." (PMID 34659235, 2021). "Our study showed the immunological changes in COVID-19 patients with DM, who presented a higher percentage of CD4+, but a lower percentage of CD8+ than those in nondiabetic patients." (PMID 33490288, 2021). "Compared to nondiabetic COVID-19 patients, diabetic COVID-19 patients are characterized by a higher percentage of CD4+ T cell and a lower percentage of CD8+ T cells and higher serum levels of IL-6, IL-2, IL-10, and INFγ." (PMID 34157054, 2021). "Flow cytometric analysis of unstimulated whole-blood samples revealed a significant increase in the percentage of IFN-γ+CD8+ T cells in COVID-19 patients relative to HVs, while IFN-γ production was comparable in CD4+ T cells, NK cells, and NKT cells between COVID-19 patients and HVs." (PMID 33232303, 2021). "We saw similar frequencies of CD4+ T-cell responses to all SARS-CoV-2 antigens, and these were highest in COVID-19 patients 1–3 months post symptom onset (means of ~3–4% of CD4+ T-cells), and were significantly higher than in individuals with other respiratory infections." (PMID 34835045, 2021). "Frequencies of KI67+ or CD38+HLA-DR+ non-naïve CD4 T cells were increased in COVID-19 patients; however, this change was not equivalent across all CD4 T cell subsets." (PMID 32669297, 2020). "No obvious differences between COVID-19 patients and healthy controls were found for any of the CD4+ T cell subtypes." (PMID 32948688, 2020). "Recovered individuals with mild COVID-19 have low CD4+ Tregs; high non-classical monocytes; low classical/non-classical monocytes." (PMID 33375675, 2020). "Moreover, examining the various subsets of T cells, the authors evidenced that both helper (CD3+CD4+) and cytotoxic T cells (CD3+CD8+) were below the normal range in subjects with COVID-19, with the T helper/suppressor ratio (Th/Ts) within normal limits." (PMID 32640747, 2020). "To characterize their cytotoxic profile, we stained the total CD4+ T cells directly ex vivo without restimulation for the cytotoxic molecules GzmA, GzmB, and perforin and compared the two age groups between COVID-19 patients and age-matched healthy controls." (PMID 32948688, 2020). "Hospitalized COVID-19 patients did not have TH2 or TH17 cytokine skewed CD4+ T cell responses, consistent with most other reports; and the CD8+ T cell response cytokine profile was similar between hospitalized and non-hospitalized cases." (PMID 33010815, 2020).
COVID-19 (continued). "We concluded that in patients with COVID-19 infection, regardless of the existence of lung lesions, in both the mild and moderate COVID-19 groups, the organism is directed to the effector profile of the CD8+ cell population, and the memory profile of the CD4+ cells." (PMID 33291439, 2020). "Instead, current TCR tracking analysis suggested enhanced recruitment of peripheral CD4+ and CD8+ T cells into lung tissues in COVID-19 patients, where they were induced to made cytokines locally and likely contributed to cytokine storm and peripheral lymphopenia." (PMID 33101705, 2020). "Some cell subsets such as NK cells (cluster 7) and CD4+ T cells (clusters 1 and 4) were quite heterogeneous between the two COVID-19 patients, so we did not examine these cell types further." (PMID 32764665, 2020). "In contrast, in post COVID-19 HC only a correlation of the CD4+ responses against spike of HCoV -OC43, but not with SARS-CoV-2 was found." (PMID 33424856, 2020). "However, SARS-CoV-2-specific CD4+ T cells, SARS-CoV-2-specific CD8+ T cells, and neutralizing antibodies were detected in the blood of most COVID-19 cases in this study, indicating the experimental approach was informative and the conclusions are reasonable." (PMID 33010815, 2020). "In fact, higher levels of CD8+ T-cells are detected in COVID-19 patients compared with controls, and a dramatic reduction of CD4+ T helper cells occurs in the most severe rather than mild COVID-19 cases." (PMID 33182802, 2020). "We also identified the percentage of HLA-DR+CD4+ T cells, PD-1+CD+4/CD8+ T cells in blood, and the neutrophil/lymphocyte ratio as useful factors for predicting critical illness and fatal outcome in patients with confirmed COVID-19." (PMID 33324414, 2020). "These collectively support that FURIN expression is induced in highly activated non-regulatory CD25+CD4+ T-cells in severe COVID-19 patients." (PMID 33178221, 2020). "Together, these data demonstrate that both CD4+ and CD8+ SARS-CoV-2-specific memory T cells are maintained and are able to produce effector cytokines after restimulation three months post-symptom onset in mildly symptomatic COVID-19 individuals." (PMID 32818218, 2020). "Recent publications identifying epitopes on CD4 and CD8 T-cells against SARS-CoV-2 in convalescent blood after natural infection represent a key step toward understanding the role of adaptive T-cell responses in COVID-19 protective immunity." (PMID 32875286, 2020). "No significant changes were seen CD4+ T, CD8+ T cells and CD4+/CD8+ ratios of patients with non-severe COVID-19 during the 4 weeks following the infection." (PMID 33261583, 2020). "However, given our understanding of SARS-CoV-2, one would predict that CD4+ T cells and CD8+ cytotoxic T (Tc) cells will play an important role in facilitating recovery and protection against severe COVID-19." (PMID 33182546, 2020). "Interestingly, robust SARS-CoV-2-specific CD4+ and CD8+ responses are seen in convalescent individuals with asymptomatic or mild COVID-19, who are showing positive serostatus." (PMID 33291245, 2020). "A low content of CD3+ T cells in peripheral blood of COVID-19 patients and a negative relationship between viral and CD4+ titers were also reported." (PMID 32916812, 2020). "Additionally, the levels of CD4+T and CD8+T and IL-6, IL-10, and NLR are potentially useful for predicting the development of COVID-19 and the severity of illness." (PMID 33134384, 2020). "(b-c) Summarized are T-cell responses shown as % of IFN-γ and/or TNF-α+ cells in CD4+ or CD8+ T cells after subtraction of the negative controls in the COVID-19 patient at three longitudinal time points and in an age-matched healthy control (spike and M/N)." (PMID 33331820, 2020). "Of interest, in patients with non-lethal COVID-19, potent virus-specific CD4+ and especially CD8+ T cell responses were observed prior to recovery from disease, indicating that cell-mediated immunity to SARS-CoV-2 is a correlate of protection." (PMID 33293664, 2020).
COVID-19 (continued). "Development and optimization of recent technologies, such as multimer staining for flow cytometry analysis, offer potential in characterizing COVID-19-specific HLA class I and II CD8+ and CD4+ T cell responses and eventually correlate their frequency with disease severity and outcome." (PMID 32708112, 2020). "In conclusion, the senescence of CD4+ and CD8+ T cells as well as the impaired function of NK cells can lead to the evasion of SARS-CoV-2 from the immune attack and clearance in patients with severe COVID-19." (PMID 32727485, 2020). "CD4+/CD8+ ratios of patients with severe COVID-19 and severe influenza A patients showed no significant changes during the 4 weeks after illness onset." (PMID 33261583, 2020). "Additionally, this is supported by evidence from COVID-19 patients when focusing on CD8+ and CD4+ T-cell responses, which are bound to immunoproteasome- and autophagy-dependent antigen presentation, respectively." (PMID 33182802, 2020). "Thus, CXCL10 is a promising surrogate marker for potentially diagnosing poor SARS-CoV-2-specific CD4+ and CD8+ T cell responses in patients with acute COVID-19." (PMID 33010815, 2020). "A second hypothesis is an increased peripheral blood frequency of a subset of polyclonal GM-CSF+ CD4 T cells capable of prodigious ex-vivo IL-6 and IFN-γ production, which has been described in COVID-19, although only in critically ill patients." (PMID 33335532, 2020). "Interestingly, the production of cytokines by CD4+ (mainly IL-2 and IFN-γ and trace amounts of IL-4, IL-5, IL-13, or IL-17α) was also reported in COVID-19 convalescents." (PMID 32916812, 2020). "It is worth noting that a much higher percentage of co-expression Tim3+PD-1+ T subsets existed in both CD4+ and CD8+ T-cells from COVID-19 patients, especially in ICU patients, suggesting an exhausted status in T-cells in these patients infected with SARS-CoV-2." (PMID 34676125, 2020). "Lymphocyte subset analyses revealed that the numbers of CD3+, CD4+, and CD8 + T lymphocytes in the patients with mild, ordinary, and severe or critical COVID-19 were significantly lower than those in the patients with asymptomatic disease (p = 0.001, p = 0.012, and p = 0.001, respectively)." (PMID 33138692, 2020). "Moreover, total lymphocytes, CD4+, and CD8+ T cells decreased in COVID-19 patients compared to healthy controls, with severe cases showing lower levels compared to the rest." (PMID 33182268, 2020). "The authors reported absence of influence of sex, CD4+ T cells counts, HIV viral load, or ART regimen associated with the occurrence of COVID-19, only older age was associated with COVID-19 infection." (PMID 33384690, 2020). "In addition, the frequencies of HLA-DR+CD38+ CD4+ and CD8+ T cells correlated with the proportion of plasmablasts in moderate and severe COVID-19+ individuals." (PMID 32669287, 2020). "Subsequent investigation of 463 patients with COVID-19 disease revealed the decreased amount of total lymphocytes, CD3+, CD4+, and CD8+ T lymphocytes in the severe type patients which indicated COVID-19 can impose hard blows on human lymphocyte resulting in lethal pneumonia." (PMID 32364527, 2020). "Patients with clinical symptoms of severe COVID-19 also commonly present with lymphopenia, including dramatically reduced numbers of NK cells, CD4+ T cells, CD8+ T cells and B cells, which has not been observed in mild cases." (PMID 33013871, 2020). "Thus, fatal COVID-19 case C92 represented an uncoordinated ADIM, with neutralizing antibodies but a largely undetectable SARS-CoV-2-specific CD4+ T cell and CD8+ T cell response." (PMID 33010815, 2020). "Those worst cases of COVID-19 had low levels of CD8+ killer T cells and CD4+ T helper cells." (PMID 33277465, 2020). "In conclusion, longer quarantine periods might be more justified for COVID-19 patients with cough, higher levels of leucocytes, neutrophils and ESR and lower levels of CD3+CD4+ lymphocytes." (PMID 33256876, 2020).